MIR4736 (microRNA 4736)
Synonyms: hsa-mir-4736
Gene: MicroRNA gene on chromosome 17 (58,335,976 to 58,336,022, reverse strand). Ensembl gene ENSG00000264399.
Homologues: Orthologues: chimpanzee MIR4736 (100% identical), macaque MIR4736 (94% identical).